LIPJ (lipase family member J)
Synonyms: LIPL1; bA425M17.2
Tractability: Small molecule: it belongs to a druggable protein family. Antibody: the Human Protein Atlas places it where antibodies can reach.
Gene: Protein-coding gene on chromosome 10 (88,586,753 to 88,606,976, forward strand). Ensembl gene ENSG00000204022.
Subcellular location (Human Protein Atlas): Plasma membrane
Pathways (Reactome):
Developmental Biology: Formation of the cornified envelope
Gene Ontology:
Molecular function: carboxylic ester hydrolase activity; hydrolase activity, acting on ester bonds; lipase activity
Biological process: lipid metabolic process
Genetic constraint (gnomAD): Loss-of-function variants: 3 observed, 7.25 expected, observed/expected ratio (o/e) 0.41, 90% interval 0.19 to 1.07. That is too few expected variants to judge how well the gene tolerates losing a copy. Missense variants: 174 observed, 176.86 expected, observed/expected ratio (o/e) 0.98, 90% interval 0.87 to 1.12. Synonymous variants: 65 observed, 64.02 expected, observed/expected ratio (o/e) 1.02, 90% interval 0.83 to 1.25.
Homologues: Orthologues: chimpanzee LIPJ (99% identical), macaque LIPJ (96% identical), rabbit LIPJ (81% identical), dog LIPJ (67% identical), Caenorhabditis elegans lipl-1 (40% identical), Caenorhabditis elegans lipl-2 (40% identical), Caenorhabditis elegans lipl-3 (40% identical), Caenorhabditis elegans lipl-5 (39% identical), Drosophila melanogaster CG31871 (36% identical), Caenorhabditis elegans lipl-6 (36% identical), Drosophila melanogaster CG31089 (35% identical), Drosophila melanogaster Lip3 (35% identical), and 20 more. Paralogues in human: LIPK (59% identical), LIPF (58% identical), LIPA (53% identical), LIPM (53% identical), LIPN (49% identical).
Diseases named in the same sentence as LIPJ in open-access papers:
LIPJ is named in the same sentence as 4 diseases in open-access papers, as found by Europe PMC text mining. Sharing a sentence is not in itself a finding about the gene and the disease. The quoted sentences say what the papers report.
Sleep apnea (1 paper, 2017). An intermittent cessation of airflow at the mouth and nose during sleep is known as sleep apnea. "Significant associations of symptoms of sleep apnea were observed with six rare variants [minor allele frequency (MAF) <1%] (located in ACE, AIFM3, LIPJ, MUC2, AP2A2, SH3BP1)." (PMID 29093733, 2017).
LIPJ also shares sentences with these, for which no sentence is quoted: infection (3 papers); endometrial cancer (1); tumor (1).